IL2 (interleukin 2)
Diseases named in the same sentence as IL2 in open-access papers (continued):
Sharing a sentence is not in itself a finding about the gene and the disease.
tumor (continued). "The results showed that compared to cGAMP, XA5508 could significantly increase the expression levels of immune factors IFN-β, IFN-γ, IL-2, IL-6, and TNFα in the mice, and significantly reduce the expression of the immunosuppressive tumor-promoting factor IL-10." (PMID 40943568, 2025). "However, it is evident that IL-2 can play a dual role in anti-tumor immunity." (PMID 39852848, 2025). "However, at low doses, IL‐2 can inhibit immune activation and promote tumor cell metastasis." (PMID 40808216, 2025). "Importantly, the combination therapy enhanced CD4+ and CD8+ T-cell infiltration, increased the production of pro-inflammatory cytokines such as IL-2, and reduced the expression of immunosuppressive factors such as IL-6, indicating an immunomodulatory effect that improved anti-tumor immunity." (PMID 41041327, 2025). "Thus, overexpression of the lncRNA H19 in the tumor microenvironment may impair T cell proliferation through diminishing IL-2 levels." (PMID 40429961, 2025). "Gene set enrichment analysis (GSEA) further showed hallmarks of anti-tumor immune responses being upregulated in the mDKN01-treated tumors compared to IgG, including interferon-gamma response, interferon-alpha response, TNFα signaling via NFκB, and IL-2/STAT5 signaling." (PMID 39885132, 2025). "However, it is important to consider that IL-2-based IT may also interact with anti-tumor effector cells." (PMID 39852848, 2025). "Consequently, low IFN-γ and IL-2 expression correlate with tumor progression." (PMID 41511353, 2025). "However, several logistical and economic barriers hinder its widespread use, including the requirement for fresh tumor tissue, the labor-intensive process of generating and expanding TILs with IL-2, anti-CD3, and feeder cells, and the eventual reinfusion into the patient." (PMID 40002184, 2025). "Therefore, several IL-2 variants with abolished IL-2Rα binding (“No-α” IL-2) have been developed to improve the safety and anti-tumor efficacy." (PMID 40046051, 2025). "Researchers combined oncolytic adenovirus (OAd) expressing TNF-α and IL-2 with CAR-T and found that it can promote M1 polarization of tumor associated macrophages and increase DC cell maturation, thereby significantly enhancing CAR-T infiltration and anti-tumor effects." (PMID 40469307, 2025). "Furthermore, the rVACV expressing both IL2 as well as TAA-derived peptides can significantly improve the therapeutic efficiency against tumors compared to that of an rVACV expressing IL2 alone in tumor-bearing mice." (PMID 41050655, 2025). "Another approach combines zoledronate and IL-2 with engraftment of Vδ2-enriched PBMCs, used for solid cancers like colorectal and pancreatic cancers – although, results have been mixed – with some patients showing tumor progression despite localized reductions." (PMID 40148988, 2025). "Our previous preclinical work demonstrated that combining oncolytic adenovirus encoding tumor necrosis factor alpha (TNF) and interleukin-2 (IL-2) with ICI could significantly improve tumor growth control and survival, even in ICI-resistant and refractory settings." (PMID 40465005, 2025). "The elevated secretion of IL-2, a critical cytokine for T cell proliferation and survival, suggests enhanced autocrine and paracrine signaling in transduced T cells, which may sustain their effector functions in the tumor microenvironment." (PMID 41376627, 2025). "Similarly, a delay in tumor growth may result from the combination of small-format IL-2 immunocytokines with high-affinity Nbs that target the tumor-specific Extra domain-B of fibronectin (EIIIB), which is present in the tumor extracellular matrix." (PMID 41562774, 2025). "Notably, IL-15 enhances CTL proliferation and memory formation, while excessive IL-2 levels may promote regulatory T cell (Treg) expansion and suppress anti-tumor immunity." (PMID 41374974, 2025).
tumor (continued). "Moreover, the level of IL‐2, an antitumor cytokine, was decreased in the coculture compared to the neuron control, suggesting that neuron–GB communication can decrease the levels of tumor suppressive factors naturally secreted by neurons and/or astrocytes." (PMID 40277152, 2025). "Furthermore, it was found through ELISA detection that in the co-culture system with the two tumor cells, the levels of IL-2, TNF-α and Gzms B secreted by the HLB-apt group were significantly higher than those of the other treatment groups and the control group." (PMID 40761795, 2025). "Therefore, the ability to selectively target EDB-FN1 within the TME and locally increase IL-2 concentrations—thereby enhancing the activation and proliferation of effector cells—could be a key strategy for effective tumor eradication." (PMID 39773310, 2025). "Boost anti-tumor immunity without the toxicity linked to traditional IL-2 therapies." (PMID 41294689, 2025). "As anticipated, the IL‐2 expression of T cells was markedly enhanced after co‐cultured with tumor cells pre‐treated with Teniposide compared to that of T cells co‐cultured with non‐treated tumor cells, and decreased by CsA pre‐treatment, indicating immunogenicity‐modulating effect of these drugs." (PMID 40583248, 2025). "However, the observation that the NK cell supporting cytokine IL2 is significantly increased in tumor tissue of Gpr4−/− animals compared to WT may hold at least part of the response." (PMID 40397803, 2025). "Thus, there is a need to consider how NK cells respond to IL-15 and how tumor-localized production of IL-15 (or IL-2, IL-21, or IL-10) is affected by therapeutics and how this therapy can be customized to address the likely insufficient cytokine receptor agonism within the TME." (PMID 40410571, 2025). "Engineered cytokines, including modified IL-2 variants, have also shown promise in early-phase clinical trials for enhancing the therapeutic index by selectively activating immune cells that target tumor cells without harming normal tissues." (PMID 40309351, 2025). "Importantly, in this murine model, IL-2 was administered locally to avoid its systemic side effects, while the anti-tumor-specific anti-GD2 mAb Hu14.18 could be administered systemically." (PMID 39852848, 2025). "However, IL-2-induced immunosuppressive T-reg populations were also sustained to tumor endpoint suggesting that therapy could be further enhanced." (PMID 39872527, 2024). "Furthermore, IL-2 may stimulate tumor cells to secrete certain angiogenic factors, promoting the formation of new blood vessels within tumors." (PMID 39867885, 2024). "The COX2/PGE2/EP signaling pathway suppresses DCs and NK cells and inhibits T cell production and responsiveness of IL-2 that limits both activation and expansion of cytolytic T cells and promotes tumor immune evasion, suggesting that COX2 blockade could restore tumor immune surveillance." (PMID 38912586, 2024). "The aAPC platform was used to rapidly amplify tumour-infiltrating lymphocytes from primary tumour specimens, based on the Carl H June designed aAPC-K32, and further co-transfection with co-stimulatory molecule 4-1BBL and allowing it to secrete IL-2, IL-15, or IL-21 cytokines." (PMID 39215816, 2024). "Thus, expansion of effector CD8 cells with IL-2 causes a progressive loss of anti-tumor killing activity, but the lack of MCJ sustains their killing activity." (PMID 38789421, 2024). "This set of observations may explain why body weight loss and anti-tumor activity could not be decoupled with not-α IL2 therapy." (PMID 38563906, 2024). "In addition to tumor cell-derived signal, one soluble factor, IL-18, may synergize with type-1 IFNs or IL-2 in the induction of ‘helper’ NK cells." (PMID 39415291, 2024).
tumor (continued). "The results support the essential role of IL-2 supplementation in the sustained expression of NKp30 on activated NK cells; NKp30 is a critical activating receptor in triggering the NK cell-mediated killing of diverse tumor cells and a prognostic biomarker in tumors including AML." (PMID 38698855, 2024). "Furthermore, IL-2 can promote the proliferation and differentiation of Treg cells, and Treg cells can inhibit the activity of cytotoxic T cells to induce immune escape, tumor recurrence, or metastasis." (PMID 39221149, 2024). "Moreover, the results proved that injection of MSCs via an adenoviral vector expressing human IL-2 boosted anticancer effects and increased overall survival rates in tumour-bearing murine models, suggesting that MSCs can be used as cytokine delivery vehicles in anticancer therapy." (PMID 39416732, 2024). "Therefore, exogenous IL-2 was required to eradicate the tumor." (PMID 38892913, 2024). "However, the function of IL-2 on DCs based tumor vaccine is unclear." (PMID 38554155, 2024). "Membrane-bound IL-2- or IL-12-expressing vvDD avoided the severe toxicity associated with systemic exposure while modulating the TME and induced superior antitumor effects, especially in combination with the PD-1 blockade, curing all or most of the mice with a high tumor burden." (PMID 38473379, 2024). "Tumor-specific synNotch receptor engineered T cells based on the synNotch pathway can independently of T cell activation, rely on bypass signaling pathways to achieve IL-2 secretion, thereby enhancing T cell proliferation and effects while reducing potential cell toxicity risks." (PMID 39342365, 2024). "The immune responses to each of the transgenes are also mediated by different arms of the immune system, primarily innate for FliC and primarily adaptive for IL-2, allowing for a more comprehensive look at which cells might be recruited and factor into tumor regression." (PMID 38787254, 2024). "Gene set enrichment analysis (GSEA) further showed hallmarks of anti-tumor immune responses being upregulated in the mDKN01-treated tumors compared to IgG, including interferon-gamma response, interferon alpha response, TNFa signaling via NFkB, and IL-2/STAT5 signaling." (PMID 38659818, 2024). "Lower tumor purity may lead to overexpression of IL2/STAT5 signaling, while tumor purity has been shown to have a negative correlation with immune and stromal scores, suggesting that subtype 2 has more immune and stromal features relative to subtype 1;this is consistent with our results." (PMID 36899891, 2023). "In addition, some tumors prompt regulatory T cells (Tregs) to express CTLA-4, leading to downregulation of CD80/CD86 expression in antigen-presenting cells, resulting in reduced production of cytokines such as interleukin 2, which affects the body’s anti-tumor capacity." (PMID 37622124, 2023). "The antitumor effect of IL-2 immunotherapy is probably derived from its ability to promote proliferation, differentiation, and survival of immune cells that include activated T, NK, and B cells in vivo, which consequently induces tumor regression and inhibits tumor growth." (PMID 36742134, 2023). "Therefore, the reduction in IL-2 circulating levels observed at M5 in patients under UM, and at M4 and M5 for dogs undergoing UM and OH, can lead to the suppression of cellular immunity, facilitating tumour recurrences and metastases." (PMID 36899784, 2023). "In addition, the combination of Nerofe and DOX also resulted in activation of the immune system against tumor cells, manifested by an increase in the immunostimulatory cytokines IL-2 and IFN-γ as well as the recruitment of NK cells and M1 macrophages to the tumor site." (PMID 37395796, 2023). "Thus, low-dose IL-2 potently upregulates immunosuppression and inhibits anti-tumor responses." (PMID 37144558, 2023).
tumor (continued). "Therefore, combined treatment with Nerofe and DOX may contribute directly to DC activation in the tumor microenvironment, in addition to their effect on IL-2 production." (PMID 37395796, 2023). "Lactobacillus, for example, can exert immunomodulatory effects like increased production of IL-2 and IL-12, antioxidant activity like production of superoxide dismutase and glutathione, and preventing DNA damage, thus, leading to decreased inflammation and tumor growth." (PMID 37588093, 2023). "Tumor cells upregulate CD38 to produce adenosine, which encourages metastasis by binding to tumor A2B receptors, causing defects in the T-cell-signaling pathway via the interruption of the IL2-induced phosphorylation of STAT 5a and STAT5b in primary and CTLL-2 T cells." (PMID 37111629, 2023). "We next asked whether IL2-REH-MSA reduced on-target, off-tumor effects compared with IL2-MSA." (PMID 37669107, 2023). "Therefore, IL-2 and tumor-specific antibody fusions are widely constructed and tested." (PMID 36839658, 2023). "An agonist of the IL-2 pathway in combination with nivolumab is being currently assessed in clinical trials for multiple human cancers as it demonstrated promising results in a phase I trial regarding clinical response and activation of tumor-infiltrating CD8 T cells." (PMID 37189417, 2023). "To assess whether IL-2 signaling is required for IL12R upregulation on tumor-reactive T cells in the TdLN, we primed naive cell trace violet–labeled (CTV-labeled) CD8+ T cells with plate-bound CD3 and CD28 agonist antibodies in the presence or absence of neutralizing IL-2 antibodies." (PMID 37669107, 2023). "In addition, we investigated whether the other HMG-CoA reductase inhibitors such as Rosuvastatin Calcium affect the anti-tumor efficacies of IL-2." (PMID 37932447, 2023). "We hypothesized that these tumor-infiltrating lymphocytes could be stimulated by IL-2 therapy." (PMID 36845705, 2023). "Interestingly, in order to overcome the tumor-induced immunosuppression and post-surgical/post-radiation reduction in T-lymphocytes, in both of these studies, investigators pre-conditioned the study participants with IL-2 prior to vaccination." (PMID 36992219, 2023). "Moreover, combined targeting of IL-2/IL-2R signaling with other immunotherapies may exhibit synergistic effects on tumor growth inhibition." (PMID 37516849, 2023). "The aim of this study is to elucidate the anticancer activity of 5-FU and IL-2-loaded cationic CD with real-time conventional and 3D cell culture studies and to evaluate the antitumor activity, antimetastatic properties, and immune response parameters in tumor- bearing animal model." (PMID 36839637, 2023). "Besides cytotoxic events unleashed by direct interaction with tumor cells, the protective role of CD8+ T cells in the tumor microenvironment is associated with release of effector cytokines (including IFN-γ, TNF-α and IL-2) that sculpts the local immune response to cancer." (PMID 37529610, 2023). "When administered together, antihistamines could enables the activation of T cells and NK cells by IL-2, resulting in the killing of tumor cells of various cancers, indicating a close connection between IL-2 and histamine signaling pathway in tumor development." (PMID 35280754, 2022). "Hence, we speculated that the anti-tumor effect of DAP probably is related to the promotion of IL-2 secretion." (PMID 36249790, 2022). "Additionally, tumor volume and mass; thymus index; spleen index; the serum cytokines IL-2, IL-4 and TNF-α; IFN-ɤ levels and tumor histopathology could be detected as detection indicators." (PMID 36080446, 2022). "We hypothesize that localization of Salmonella to the TME will generate a local source of inflammation that will drive effective immune activation and priming of T cells while administration of Alb-IL2 will promote enhanced activation and proliferation of tumor reactive T cell clones." (PMID 35962391, 2022).
tumor (continued). "The loss of IL-2 production occurred early in T cell depletion, and IL2 expression was higher in the low-risk group than in the high-risk group, which also represented a residual cytotoxicity and tumor cell clearance function of CD8+ T cells in the low-risk patients." (PMID 36704353, 2022). "IL-2 (400 U/ml) might also favor ILC3 cytotoxic responses leading to increased tumor cell lysis." (PMID 35300331, 2022). "HB tumor rupture might not be predictive of poor prognosis with the risk of peritoneal dissemination/relapse, in which peritoneal perfusion with interleukin-2 could play a role." (PMID 35391745, 2022). "Since a boost of serum IL-2 concentration following IL-2 plasmid electrotransfer resulted in significant growth inhibition of indirectly treated tumors (abscopal effect), we further aimed to analyze the effect of IL-2 on tumor growth following electroporation-based treatments." (PMID 35954434, 2022). "In addition, tumor cells alter infiltrating immune cells by secreting and releasing immunosuppressive substances such as transforming growth factor, interleukin-2, interleukin-10, and vascular endothelial growth factor into the microenvironment, which impede their antitumor activities." (PMID 36275664, 2022). "As proof of principle, we first validated the contribution of the Neoscreen approach by interrogating TILs from two tumor specimens (patients 6 and 7) where we could readily identify four neoepitope reactivities among (conventional) TILs expanded with IL-2." (PMID 34782741, 2022). "In addition, IL-2 may protect tumor cells from immune surveillance, perhaps via the promotion of Tregs." (PMID 35740551, 2022). "IL-2 and IL-10 are a type of cell growth factor in the immune system that can regulate the cell activity of white blood cells in the immune system, promote the proliferation of Th0 cells and CTLs, and also participate in the antibody response, haematopoiesis and tumor surveillance." (PMID 35445056, 2022). "High dose IL-2 therapy was one of the earliest oncologic immunotherapies and it is an effective treatment of metastatic RCC, associated with an objective response in tumour size in over 40% of selected patients and with durable complete remissions in around half of those patients." (PMID 35741162, 2022). "Notably, muscle transfection by IL-2 coding plasmid also inhibited tumor growth." (PMID 35954434, 2022). "Therefore, most tumor-specific T cells responding to IL-2 are PD-1+TIM3+ cells." (PMID 35104810, 2022). "The ratio of CD4+/CD8+ T cells and the levels of their characteristically secreted cytokines, IFN-γ and IL-2, were induced to decrease by the tumor cells, while these immunosuppressive issues could be reversed via inhibiting the activation of STAT3 pathway by rosmarinic acid." (PMID 36615387, 2022). "Differences in gene expression between tumours growing in immunocompetent and immunodeficient hosts were related to changes in the expression of extracellular matrix proteins and changes in interferon gamma and Il-2 signaling, consistent with the differences in T-cell abundance (PC2)." (PMID 36525288, 2022). "Recently, it is reported that inhibiting sEV PD-L1 secretion could improve the efficacy of anti-PD-L1 and anti-cancer immunity because tumor-derived sEV and sEV PD-L1 contribute to tumor growth and immune evasion by inhibiting T cell activity, such as NF-κB, IL-2, and IFN-γ activation." (PMID 36077620, 2022). "A longitudinal follow-up of a patient with metastatic melanoma who relapsed upon interleukin-2 treatment revealed an activation of the β-catenin pathway, associated with the absence of infiltrating CD8+ T cells and decreased chemokine expression in the recurrent tumor." (PMID 35432344, 2022).